F13A1 (coagulation factor XIII A chain)
Diseases named in the same sentence as F13A1 in open-access papers (continued):
Sharing a sentence is not in itself a finding about the gene and the disease.
tumor (31 papers, 2009 to 2026). "At transcriptional levels, our data show that F13A1+ Mφs resemble the M2‐like macrophages, an anti‐inflammatory subtype that has been implicated in promoting tumour growth and suppressing immune response." (PMID 39601163, 2024). "F13A1 contributes to tissue remodeling processes that can be co-opted during tumor invasion and metastasis, potentially modifying the tumor microenvironment." (PMID 41155404, 2025). "Genes that were identified as markers of TAM2 in human ccRCC cells, including Fn1, F13a1 and Gas7 were more highly expressed in Mono-macrophage cluster 2 cells from tumours than from normal kidneys." (PMID 40473819, 2025). "We also identified F13A1 as a possibly novel tumor marker for GBM which can support GBM malignant tumor cells by promoting fatty acid metabolism in GBM macrophages." (PMID 40002669, 2025). "The overexpression of F13A1 in tumour‐infiltrating Mo/Mφs compared to adjacent non‐cancerous tissues suggests its potential as a diagnostic and prognostic marker for MPLC." (PMID 39601163, 2024). "The presence of F13A1+ Mφs in MPLC suggests their involvement in the formation of the TME, potentially linked to immune evasion mechanisms and a tumour‐promoting phenotype specific to MPLC." (PMID 39601163, 2024). "The results unequivocally demonstrated that CD1C and F13A1 were significantly up‐regulated in multiple primary tumours compared to single‐primary tumours." (PMID 39601163, 2024). "For instance, CellNeighborEX found that F13a1 is highly expressed when Monocyte cells contact Tumor cells (Fig EV3A)." (PMID 37815040, 2023). "Additionally, we conducted an in‐depth assessment of CD1C and F13A1 expression levels on myeloid cells across four distinct groups and compared myeloid cells in tumour tissues from MPLCs and SPLCs." (PMID 39601163, 2024). "The enrichment of F13A1+ Mφs in MPLCs compared to SPLCs suggests their involvement in the formation of TME, as well as the distinct characteristics and behaviour of MPLC tumours, potentially linked to immune evasion mechanisms and a tumour‐promoting phenotype specific in MPLC." (PMID 39601163, 2024). "F13A1 was an important coagulation-related gene encoding factor XIII subunit A (FXIII-A), which was a transglutaminase involved in hemostasis, wound healing, tumor growth, and apoptosis." (PMID 38022584, 2023). "First, we need to clarify the specific mechanism of F13A1 in GBM, including how it regulates macrophage metabolism and how this regulation affects the growth and invasion of tumor cells." (PMID 40002669, 2025). "F13A1 is a component of coagulation factor XIII and functions as a transglutaminase that can also cross-link many proteins involved in tumor growth, wound healing and apoptosis." (PMID 40264151, 2025). "The consistent up‐regulation of F13A1 and CD1C across multiple nodules in different patients underscores their significance in the context of multiple primary tumours." (PMID 39601163, 2024). "The analysis revealed a strong distribution preference of F13A1+ Mφ and CD1C+ cDC2 in tumours from MPLCs, as compared to tumours from SPLCs and normal tissues from both MPLCs and SPLCs." (PMID 39601163, 2024). "Furthermore, the expression levels of F13A1 and CD1C in myeloid cells were significantly higher in MPLC tumours than SPLC tumours." (PMID 39601163, 2024). "We assessed the distribution pattern of myeloid subsets in the same manner as in our own data, and identified the enrichment of F13A1+ Mφ (OR = 1.60) and CD1C+ cDC2 (OR = 2.03) in multi‐primary tumours compared to solitary primary tumours and adjacent non‐tumour tissues." (PMID 39601163, 2024). "MSGN1, ISM2, HAS1, RETN, MMP19, C1QTNF1, and F13A1 were all involved in the regulation of tumors, but their involvement in the regulation of tumor immunity is not clear." (PMID 34177903, 2021).
tumor (continued). "Therefore, the downregulation of F13A1 in SCLC is surprising, but may indicate a novel tumor suppressing role of blood coagulation in SCLC pathogenesis, which is supported by the similar downregulated expression of F11 in SCLC patients in the current study." (PMID 34996345, 2022).
cancer (21 papers, 2007 to 2026). A tumor composed of atypical neoplastic, often pleomorphic cells that invade other tissues. "According to studies, the F13A1 gene is involved in the development of cancer, with dysregulation of excessive platelet activation, thrombosis and its association with inflammation." (PMID 38435719, 2024). "Some of the significant cancer hallmark terms are epithelial-mesenchymal transition (MSX1, CXCL12, SCG2, SLIT2), KRAS signaling up (F13A1, ADAMDEC1), inflammatory response (CCL5, VIP), IL-6/JAK/STAT3 signaling (CXCL13)." (PMID 35486660, 2022). "Integration with publicly available single-cell sequencing data revealed that these proteins were mostly macrophage and monocyte-associated with malignant features (TYMP, FCER1G, FCGR1A, SYK, and F13A1), except NNMT, which was highest in cancer-associated fibroblasts (Table EV4)." (PMID 41233595, 2026). "The expression of F13A1 was up-regulated in some cancers, including GBM, LGG, KIRC, and so on." (PMID 40002669, 2025). "The expression of F13A1 was down-regulated in other cancers including UCEC, BRCA, CESC, and so on." (PMID 40002669, 2025). "This suggested that F13A1 might play a different role in different cancers." (PMID 40002669, 2025). "The BAMBI (Vanhara and Souček, 2013), LCN2, F13A1, CDKN2A, SLIT2, and CLU were reported to individually play a role in cancer development and progression." (PMID 33585439, 2020). "We find that the genes specifically expressed in the supratentorial tumors from these publications (such as HLA-DRA, LYZ, CD74, F13A1, and TRIM22) tend to be expressed in cells within the microglia-type cluster, whereas the infratentorial tumors have higher expression of cancer cell-related genes." (PMID 31427603, 2019). "Proteases present in malignant tumours but not in normal skin included: PGC, BAP1, caspase-8, F13A1, MMP11, MMP23, MMP25, MMP26 and granzyme-A." (PMID 35327667, 2022).
infection (4 papers, 2017 to 2025). The state of being infected such as from the introduction of a foreign agent such as serum, vaccine, antigenic substance or organism. "In leukocytes, expression of F13A1 (forming coagulation FXIII) correlated with TLR7, TLR9, RIG-I, MDA5, and LGP2, and with infection the correlations changed to TLR6 and CGAS." (PMID 40825056, 2025).
hematologic disorder (2 papers, 2021 to 2022). A disease involving the hematopoietic system. "In addition, genes associated with hematological disease (e.g., PDE7A, LMAN1, F13A1, OLR1) and mitochondrial biogenesis and redox (e.g., NOS3, ALDH5A1, PRXL2A, SLC25A13, CPT2) were also significantly altered in BPD patients." (PMID 35484630, 2022).
F13A1 also shares sentences with these, for which no sentence is quoted: dermatofibroma (8 papers); psoriasis (4); dermatofibrosarcoma protuberans (3); juvenile xanthogranuloma (3); acute myocardial infarction (2); atherosclerosis (2); cardiovascular disease (2); histiocytic neoplasm (2); Histiocytosis (2); neurofibroma (2); thrombosis (2); acne (1); angiosarcoma (1); asthma (1); atrophic gastritis (1); Barrett esophagus (1); bleeding disorders (1); blue nevus (1); brain cancer (1); calcifying fibrous tumor (1); cardiac ischemia (1); clear renal cell carcinoma (1); cleft lip (1); colon adenocarcinoma (1); cystic fibrosis (1); depression (1); dermatitis (1); endothelial dysfunction (1); epithelial dysplasia (1); Erdheim-Chester disease (1).
A further 35 diseases each share a sentence with F13A1 in 1 paper.